IL6 (interleukin 6)
Diseases named in the same sentence as IL6 in open-access papers (continued):
Sharing a sentence is not in itself a finding about the gene and the disease.
tumor (continued). "In our study, four key indicators were found to better predict tumor metastasis, namely IL-6, IL-8, lymphocyte percentage, and IL-12p70." (PMID 36157224, 2022). "This persistent inflammation as well as the proinflammatory cytokines IL-1 and IL-6 promote tumor formation in lung and breast cancer models." (PMID 36013319, 2022). "argued that chemotherapy-resistant HCC cell-released IL-6 boosts the silencing and activity of MDSCs and, when anti-IL6 neutralizing antibody is combined with 5-FU chemotherapy, tumor growth is significantly decreased." (PMID 36457492, 2022). "High risk HPV promote upregulation of IL6 and TLR4, resulting in an inflammatory environment that can contribute to tumor development." (PMID 35468924, 2022). "CAF-derived IL-6 can impair the activity of tumor-infiltrating T cells and neutralization of IL-6 reverses anti-PD-L1 resistance in an HCC mouse model." (PMID 36457492, 2022). "Concentration of pro‐inflammatory and pro‐angiogenic cytokines including IL‐1a, IL‐2, IL‐6, IL‐10, IL‐12, and IL‐17A, in peripheral blood of tumor bearing mice receiving anti‐MUC1 nanobody was significantly lower compared to the PBS receiving group." (PMID 34694686, 2022). "The high level of IL-6 in the tumor microenvironment indicates a strong relationship between inflammation and cancer." (PMID 35884907, 2022). "CAFs can also secrete the cytokines cardiotrophin-like cytokine factor 1 (CLCF1) and interleukin 6 (IL6) to directly stimulate the growth of tumor cells." (PMID 35711936, 2022). "Animal experiments have shown that tumor-derived factors such as IL-6, CXCL16, IFNγ, TNFα, and IGFBP-3 positively regulate the expression of CD38, and high expression of CD38 can enhance the immunosuppressive and tumor-promoting capacity of MDSCs." (PMID 36119033, 2022). "Recruitment and differentiation of TAM macrophages at tumor sites are mainly induced by granulocyte–macrophage colony-stimulating factor (GM-CSF), CCL2, VEGF, IL-6, and IL-8, which are related to hypoxia, acidity, and inflammation of tumor tissues." (PMID 36209263, 2022). "Il17a and Il6, both of which possess a dichotomic role in tumor immunity were also increased, further indicating that NK cells bolstered the anti-tumor function of m-reMAIT cells." (PMID 36551916, 2022). "It has been reported that activation of the IL-6/STAT3 pathway downregulates the expression of genes to promote tumor angiogenesis." (PMID 36286020, 2022). "It has been well documented that HAMP expression is positively regulated by BMP2/4/6/7 and IL6, while tumor-derived IL6 suppresses TH1 cell functionality." (PMID 36532749, 2022). "In breast cancer, a stimulation expressed-TLR4 tumor with LPS promoted cancer cell proliferation via upregulation of IL-8 and IL-6 production." (PMID 35309296, 2022). "It was recognized over 30 years ago that the polyfunctional cytokine interleukin-6 (IL-6) was an almost invariant presence at the host-tumor interface." (PMID 35406728, 2022). "Fibrinogen is upregulated by cytokines, such as interleukin (IL)-6 in the liver; thus, the plasma fibrinogen level can reflect tumor progression." (PMID 36313734, 2022). "Pedersen revealed a link among exercise, epinephrine, and interleukin-6 to natural killer cell mobilization, redistribution, and ultimately to the control of tumor growth." (PMID 35158757, 2022). "So, IL-6 has two ways of impacting the formation of the aneurysm’s direction, first by promoting tumor invasion into the intracranial artery or secondly by increasing the chance of a distant embolization of the cardiac myxoma." (PMID 36675669, 2022). "Further research highlighted concerns about the efficacy of this therapy because of the adaptibility of tumor promoting growth factor like IL-6." (PMID 36299504, 2022). "For macrophages, repolarization is induced to a tumor-suppressive type characterized by the production and release of proinflammatory cytokines, including IL-1β, TNFa, and IL-6." (PMID 36013403, 2022).
tumor (continued). "A study by Iwahasi17 suggested that HCC tumor malignancy, through the IL-6/STAT3 pathway, is affected by the activation of hepatic stellate cells." (PMID 37829248, 2022). "IL-6/JAK/STAT3 signaling strongly inhibits anti-tumor immune response through negative regulatory effects of T cells and natural killer cells, which contributes to the formation of primary immunotherapy resistance." (PMID 35508972, 2022). "IL-6 has been established as a driver of carcinogenesis and tumor progression in PCa, while less is known about the role of ciliary neurotrophic factor (CNTF), a member of IL-6 type cytokine family." (PMID 36497399, 2022). "IL1A and IL6 are two crucial inflammatory cytokines in macrophages, playing important roles in tumor development." (PMID 36071472, 2022). "It was reported that HCC-derived IL-6 hindered the recruitment of MDSCs and enhanced their immune inhibitory function to hamper anti-tumor immunity." (PMID 36293184, 2022). "Magidey-Klein and co-workers put forward a new role of tumour-derived IL-6 in driving the differentiation of HPSCs toward pro-metastatic MDPs." (PMID 36429126, 2022). "On the same line, IL6 can promote tumor cell expansion and, accordingly, elevated levels of this cytokine were reported to correlate with an increased risk of cancer progression in NSCLC patients." (PMID 36555441, 2022). "IL-6 plays a major role in the pathogenesis and development of malignancies, promotes tumor growth, inhibits apoptosis, induces angiogenesis and influences the overall metabolism in cancer patients." (PMID 36015338, 2022). "The induction of STAT3 by IL-6 or stress factors leads to progress in the self-renewal of prostate CSCs and tumor-propagation." (PMID 36359888, 2022). "COPD promotes tumour proliferation and angiogenesis through the production of chemokines and cytokines, such as tumour necrosis factor-α, interleukin-1 and interleukin-6." (PMID 35267589, 2022). "Surgical tumor resection can induce immunosuppressive activities by inducing pro-inflammatory and pro-tumorigenic cytokines such as IL-1β, IL-6, IL-10 CCL-2 and TGF-β, which recruit immunosuppressive cells such as MDSCs." (PMID 36611932, 2022). "In TME, IL-6 can be produced by a variety of cells, including macrophages, neutrophils, fibroblasts, and tumor cells themselves." (PMID 36291659, 2022). "SH2D4A was identified as a chromosome 8p tumor suppressor and positively correlated with effector and regulatory T cell infiltration by blocking IL-6 signaling in HCC, which implies its crucial role in HCC." (PMID 36147313, 2022). "Inflammatory cells can change the tumor microenvironment through overproducing cytokines, including IL-2, IL-6, and TNF-α, thus promoting tumorigenesis and the proliferation, migration, and immune escape of tumor cells." (PMID 35872847, 2022). "Regulates the balance between “tumor-promoting bacteria” and “tumor-suppressing bacteria” and inactivated the NF-κB/IL-6/STAT3 pathway." (PMID 36051242, 2022). "Activation of TLRs in the tumor cell induces the production of proinflammatory cytokines IL-6 and IL-8, a strong neutrophil chemoattractant, and vascular endothelial-derived growth factor (VEGF), which is a key factor in promoting angiogenesis." (PMID 35742983, 2022). "Adipocytes produce several paracrine and endocrine factors known as adipocytokines, including leptin, adiponectin, tumor necrosis factor (TNF)-α and interleukin 6, potentially affecting tumor growth." (PMID 35233007, 2022). "Some studies have shown that IL-6 is involved in increasing the proliferation of tumor cells in colon and NFκB/IL-6/STAT3 signaling seems to play a crucial role in CAC development." (PMID 35410210, 2022). "It has been reported that IL-6 can enhance tumor angiogenesis and metastasis either directly or by inducing the expression of well-known angiogenic and metastatic molecules such as VEGF, MMP2 and MMP9 in cancer cells." (PMID 35300689, 2022).
tumor (continued). "Some nuclear pSTAT3 accumulation was also evident in the IL-6pos regions of tumor stroma, suggesting potential autocrine IL-6 signaling in these areas." (PMID 35565421, 2022). "MDSCs induce the EMT program by releasing various cytokines, such as PGE2, TGFβ, EGF, and HGF, and strengthen the tumor stemness using IL6 that activates STAT3 and NOTCH pathways." (PMID 36211375, 2022). "Tumor-EV-derived MIR-92A has also been shown to alter macrophages to increase their production of IL-6 which, in turn, stimulates cancer cells’ proliferation, migration and invasion." (PMID 36010994, 2022). "IL-6 in the TME has been reported to play an important role in tumor progression and chemoresistance via activation of the JAK/STAT3 pathway." (PMID 35615263, 2022). "Tumor cells are known to produce several cytokines, such as TGF-β, VEGF, IL-6, and IL-10, which mediate the suppression of DC maturation and immune responses in the tumor microenvironment." (PMID 35584505, 2022). "For example, TNF-α, IL-6, IL-8, and IL-23 mediate inflammation resulting in tumor growth, and TGF-β and CXCL12/CXCR4 mainly promote metastasis." (PMID 36237303, 2022). "Locally produced IL-6 enhanced cancer-targeting functions of tumor-infiltrating macrophages and immune cells." (PMID 35406728, 2022). "Further and consistent with the primary tumor, lungs of wounded mice revealed significantly reduced anti‐tumoral M1 macrophage cytokine expression of IL‐6 (p < 0.05)." (PMID 36325601, 2022). "IL6-JAK-STAT3 signaling pathway has a great impact on several ways of tumor progression, such as migration, invasion, and angiogenesis, and it also has the potential for prognostic evaluation in KIRC." (PMID 36188220, 2022). "Tumor cells, as well as host immune cells, contribute to this inflammatory state by releasing pro-cachectic cytokines such as TNFα, IL-1, IL-6, and IFN-γ." (PMID 35740519, 2022). "Interleukin-6 (IL-6) and interferon-γ (IFN-γ) were significantly upregulated after DOX-JQ1@Gel implantation and IFN-γ causes the expression of PD-L1 in tumor cells." (PMID 35953828, 2022). "The discovery of a specific mode of IL-6 delivery from stroma to tumor through EVs, however, likely confers a particularly calibrated and potent effect." (PMID 36266345, 2022). "As an inflammatory cytokine from the cancer microenvironment, Interleukin-6 (IL-6) was reported to promote tumor progression via activating multiple signaling pathways, including JAK/STAT3, AKT/mTOR and Raf/MEK/ERK pathways." (PMID 35372504, 2022). "In TNBC cell lines, inhibition of IL-6 and IL-8 expression dramatically reduced colony formation and cell survival in vitro and prevented tumor engraftment and growth in vivo." (PMID 35163731, 2022). "The tumor microenvironment has a high level of interleukin-6 (IL-6), which is a growth factor to stimulates cell growth and also generates some degrees of resistance in radiotherapy and chemotherapy." (PMID 36439106, 2022). "In tumor cell lines, overexpression of IL-6 increased myeloid cell recruitment, angiogenesis, and metastasis." (PMID 35159388, 2022). "Signal transducer and activator of transcription 3 (STAT3) is the main transcription factor mediating IL-6-induced signaling in tumor and immune cells, whereas interferon-γ (IFN-γ) signaling activates the closely related STAT1 protein." (PMID 35267462, 2022). "The engineered bacteria were tested for their ability to remove IL-8 and IL-6 from the supernatant of cancer cells and to bind tumor antigens EpCAM or HER2 on HEK293 cells." (PMID 35155394, 2022). "IL6 is an inflammatory cytokine that modulate growth and differentiation in tumor cells through STAT3 signaling pathway." (PMID 35399006, 2022). "To further confirm the role and effect manner of IL6, we created a conditioned medium (CM) by collecting the cell supernatant generated from tumor cells cultured with LPS." (PMID 35710492, 2022).
tumor (continued). "Elevated levels of circulating IL-6 are believed to be mediating the tumor cachexia phenotype, including muscle wasting." (PMID 34846534, 2022). "Treatment with IL30 also upregulated tumor progression genes, such as Ar (3.27 times), Bcl2 (3.25 times), IL6 (3.90 times), Cav2 (7.60 times), Ndrg3 (4.5 times), Sept7 (4.10 times) and Sfrp1 (7.46 times)." (PMID 36224639, 2022). "Our results showed that TNBC tumor cells secreted elevated levels of proinflammatory markers including IL-6, IL-8, VEGF, and higher NF-κB transcription factor activation as compared to normal breast epithelial cells." (PMID 36564457, 2022). "STAT3 is an oncogenic transcription factor regularly activated in cancer and tumor-related myeloid cells by the IL-6." (PMID 35264191, 2022). "IL6 is a pleomorphic cytokine involved in various biological processes, such as inflammation and tumor development." (PMID 35672352, 2022). "In the first instance, IL-6 immunoreactivity was observed in HER2neg/pSTAT3neg tumor cell foci adjacent to clusters of HER2pos/pSTAT3pos cells (Pattern 1)." (PMID 35565421, 2022). "Regarding myeloid cells, immunization of IL-6-/- mice with gDE7 enhanced DC migration into the tumor microenvironment." (PMID 36405719, 2022). "The reduction in IL-5 (p < 0.05), IL-6 (p < 0.01), and IL-10 (p < 0.05) in the tumor and spleen of the IHS-treated ApcMin/+ mice was further confirmed through ELISAs." (PMID 36014805, 2022). "STAT can induce tumor cell apoptosis by interfering with the MARK signaling pathway or down-regulating interleukin (IL-6) expression and STAT3 of interferon-alpha/beta signaling." (PMID 36311733, 2022). "Tumor cells can increase the number of platelets in blood via thrombopoietin, IL-6 or leukemia inhibitory factor, and in turn, platelets facilitate tumor cell survival and escape from immune clearance mechanisms." (PMID 35958590, 2022). "IL6 levels in serum and tumor sites are elevated in several cancers, including BC60, and are usually accompanied by poor prognosis and low survival rates in BC patients." (PMID 35962042, 2022). "In a subset of tumors, co-localization of HER2 and activated STAT3 was evident in isolated tumor foci with IL-6 expressed in either adjacent tumor foci, adjacent stroma, or co-expressed with HER2 and pSTAT3." (PMID 35565421, 2022). "Here, we aimed to describe the interaction between the AnxA1/FPR1 and the Interleukin-6 (IL-6) signaling pathways and their role in the tumor microenvironment (TME)." (PMID 35626741, 2022). "This highlights the importance of recognizing both baseline IL-6 and IL-8 values as interacting prognostic factors to cover both of liver inflammation/injury and tumor-related factors." (PMID 33855585, 2022). "The IL-6/JAK/STAT signaling pathway is one of the main signaling pathways involved in tumor migration and invasion." (PMID 35448036, 2022). "In terms of function, myCAFs mainly mediate the production of extracellular matrix components to promote tumor metastasis and invasion, while iCAFs can secrete some cytokines such as IL-1 and IL-6 to promote tumor growth and mediate immunosuppression." (PMID 36152055, 2022). "IL6 can also induce pro-angiogenic effects, inducing VEGF expression in tumour-associated endothelial cells through STAT3 and MAPK, while the IL6 inflammatory loop can activate mechanisms linked to drug resistance." (PMID 34834425, 2021). "Studies have found that HBV can be involved in the translation and nuclear translocation of angiogenin (ANG) through IL-6-mediated pathways, thereby promoting tumor cell proliferation." (PMID 34976809, 2021). "Chemoresistant GBM cells promote the suppression of TLR4 expression in tumor-infiltrating macrophages that release cytokines such as IL-6 and IL-10 and support a tumor-promoting ME." (PMID 34646780, 2021).
tumor (continued). "In TNBCs and many other human cancers, IL-6 is recognized as a major cytokine produced by multiple cell types within the tumor microenvironment, and which has important roles in tumor development and progression." (PMID 34445170, 2021). "Gene set enrichment analysis (GSEA) found tumor hallmarks including angiogenesis, IL6-JAK-STAT3-signaling, reactive oxygen species pathway and oxidative phosphorylation were enriched in high-risk UM patients." (PMID 33682883, 2021). "In a mouse model, IMO-2055, a TLR 9 agonist, exerted anti-tumor effects by increasing IL-6 and 12 levels with only little inflammatory reaction." (PMID 34476575, 2021). "We also recently established IL-6 as a crucial cytokine of equal importance for both inflammation and tumor development, suggesting that IL-6 is a significant tumor promoter during the early stages of CRC." (PMID 33578709, 2021). "IL-6 is an inflammatory cytokine with the ability to induce tumor growth, metastasis, and resistance to chemotherapy in a variety of tumor cells." (PMID 33435539, 2021). "For this reason we adoptively transferred bone marrow B cells derived from tumor-bearing IL6-/-;Eμ-myc mice into either IL6+/+ or IL6-/- recipient mice." (PMID 33651821, 2021). "TNF-α, IL-6, and IL-8 are particularly characteristic tumorigenic cytokines involved at the onset and all subsequent stages of tumor development, including promotion, progression, and metastasis." (PMID 34503198, 2021). "Our mechanistic study demonstrated that TP‐16 and anti‐PD‐1 synergistically reduced the serum level of IL‐6, a critical immunosuppressive factor, in tumor‐bearing mice." (PMID 33283987, 2021). "Our models support an indirect role for tumor‐expressed EphA2 in modulating osteoclast differentiation through regulation of IL‐6." (PMID 33869989, 2021). "Inflammatory markers levels are dependent on tumor types, but high level of CRP, IL-6, IL-1β have been associated with poor prognosis." (PMID 34867341, 2021). "Bone resorption during osseous disease results in the release of sequestered transforming growth factor beta (TGFB), which together with interleukin 6 (IL-6) produced by bone marrow stromal cells, can act on resident T cells to preclude tumour killing." (PMID 34128831, 2021). "This was explained by the fact that CD14high tumor cells have a higher production of IL6, IL8/CXCL5, CXCL1, CXCL2, M-CSF, VEGF-A, FGF-2 than CD14low tumor cells." (PMID 34572939, 2021). "Myofibrotic CAFs (myCAFs) show alpha-smooth muscle actin (α-SMA)high interleukin-6 (IL-6)low myofibroblastic features, are activated by direct contact with tumor cells, and are located in the periglandular region." (PMID 34336821, 2021). "Under inflammatory conditions, NF-κB-induced IL-6, secreted from immune cells or tumor cells, can lead to cancer progression and metastasis via the IL-6/signal transducer and activator of transcription 3 (STAT3) signaling pathway." (PMID 33578830, 2021). "Specifically, IL-6-educated MDPs adoptively transferred into met-low tumor-bearing mice, resulting in increased metastasis, in a similar phenotype found in met-high tumors." (PMID 34140316, 2021). "Herein, we revealed that inflammatory cytokine IL6‐triggered EMT significantly increases tumour blood vessel permeability by specifically increasing the packaging of miR‐27b‐3p in cancer‐derived exosomes." (PMID 34936736, 2021). "Further, constitutive activation of STATs, resulting from either prolonged IFN signaling, other extracellular stimulus (e.g., IL-10 and IL-6), and tumor cell-intrinsic alterations, has been largely correlated with radioresistance." (PMID 34830176, 2021). "Combination blockade of IL-6 and PD-L1 led to increased Th1 T cell infiltration and decreased tumor growth." (PMID 34290984, 2021). "Interleukin 6 (IL-6) is among those interleukins most commonly elevated in the tumor microenvironment and has been shown to stimulate thrombopoiesis." (PMID 34417915, 2021).